CIC (capicua transcriptional repressor)
Diseases named in the same sentence as CIC in open-access papers (continued):
Sharing a sentence is not in itself a finding about the gene and the disease.
glioma (57 papers, 2012 to 2025). A benign or malignant brain and spinal cord tumor that arises from glial cells (astrocytes, oligodendrocytes, ependymal cells). "Prior studies have demonstrated that in low‐grade IDH‐mutant gliomas, TERTp mutation is associated with genetic alterations in CIC, FUBP1, and MYC, as these genes are closely related to 1p/19q deletion." (PMID 39804195, 2025). "A total of 7341 glioma tumor samples were classified based on histology subtypes and characterized for CIC mutation status." (PMID 37291277, 2023). "Studies have shown that the presence of CIC mutations is associated with better survival in glioma patients, which is consistent with the better prognosis in our low-risk group of patients." (PMID 36325335, 2022). "CIC mutation was also highly expressed in the low-risk group, which is associated with better survival of glioma." (PMID 36060266, 2022). "EGFR (21%), PTEN (17%), and NF1 (12%) mutations in the high-glioma risk score group and CIC (28%), FUBP1 (11%), and NOTCH1 (10%) mutations in the low-risk score group were identified, and the mutation frequency of these genes was greater than 10%." (PMID 36311792, 2022). "In this study we aim to identify the value of CIC mutations in gliomas by analyzing the relationship between CIC mutations and the clinical characteristics, key molecular markers, and patient survival." (PMID 32676453, 2020). "In conclusion, our results support CIC mutation status as a valuable diagnostic and prognostic biomarker of lower-grade glioma." (PMID 32676453, 2020). "Our study identified CIC as a potential prognostic factor in glioma which has close associations with survival." (PMID 32676453, 2020). "Our results in conjunction with other studies indicate that CIC mutations play a critical role in oligodendroglioma development and form a molecular feature distinctive of this glioma subtype." (PMID 24086756, 2013). "Additionally, the low-risk group glioma samples possessed more frequent mutations in IDH, ATRX and CIC genes, whose mutations possess anti-tumor effects in gliomas." (PMID 36845382, 2023). "In all gliomas analyzed together, CIC mutations were associated with younger age (46 yrs." (PMID 37291277, 2023). "In addition, a higher missense mutation rate of the Drosophila gene capicua (CIC) was found in Cluster 2, which has been shown to correlate with better survival in glioma patients, even with the co-occurrence of favorable markers including IDH mutation and 1p/19q codeletion." (PMID 35990696, 2022). "Importantly, IDH mutated, 1p/19q codeleted gliomas were characterized by mutations in CIC, FUBP1, NOTCH1, and TERT promoter, suggesting these mutations could serve as oligodendroglial lineage markers." (PMID 27556304, 2016). "Cases in G1 group were rich in IDH, CIC, and NOTCH1 mutations that have been confirmed to be enriched in low grade glioma." (PMID 37322408, 2023).
glioma (continued). "Additional loss-of-function mutations in far-upstream element binding protein (FUBP1) on 1p31.1 and capicua transcriptional repressor (CIC) on 19q13.2 are observed in over 60% of 1p/19q-codeleted gliomas." (PMID 29616301, 2018). "The latest evaluation of molecular subgroups of gliomas identified ATRX, CIC, and FUBP1 mutations, and allowed distinguishing patients with IDH1/CIC/FUBP1 or IDH1/ATRX mutations." (PMID 27834917, 2016). "The mutational analysis of 363 brain tumors reported the distribution of ATRX, CIC (homolog of the Drosophila capicua gene), and FUBP1 mutations in gliomas." (PMID 24202337, 2013). "The mutational analysis of 363 brain tumors reported here represents the largest effort to date to define the distribution of ATRX, CIC, and FUBP1 mutations in gliomas." (PMID 22869205, 2012). "Moreover, recurrent CIC mutations are found in gliomas (exclusively in those possessing an IDH1/2 mutation), implicating CIC as a potential tumour suppressor in this cancer type." (PMID 34767259, 2022). "MR imaging and its derived image of gliomas with CIC mutation appears more complex and non-uniform but are associated with lower malignancy." (PMID 32676453, 2020). "Moreover, the EGFR and MUC16 mutations were also significantly enriched in cases within high‐risk group, while mutations in CIC, NOTCH1, ATRX, and CDH12 occurred more frequently in the low‐risk group, these characteristics are consistent with the update WHO CNS5 classification of glioma." (PMID 35985661, 2022). "This analysis defined two highly recurrent genetic signatures in gliomas: IDH1/ATRX (I-A) and IDH1/CIC/FUBP1 (I-CF)." (PMID 24202337, 2013). "This analysis allowed us to define two highly recurrent genetic signatures in gliomas: IDH1/ATRX (I-A) and IDH1/CIC/FUBP1 (I-CF)." (PMID 22869205, 2012). "CIC is a transcriptional repressor of ETS transcription factors and other genes downstream of the MAPK pathway and is a recurrently inactivated tumor suppressor gene in gliomas and other cancer types." (PMID 35706047, 2022). "The resulting three categories were as follows: I-A (IDH1/ATRX mutation), I-CF (IDH1/CIC/FUBP1 mutation), and I-X gliomas (not I-A or I-CF)." (PMID 29026176, 2017).
glioma (continued). "These occur across a spectrum including conventional CIC-altered sarcoma, high-grade neuroepithelial tumor, and even rare lower-grade glial tumors, indicating that not all the intracranial CIC-fused tumors are CIC-altered sarcomas, especially those with CIC::LEUTX genetic fusion." (PMID 38926750, 2024).
sarcoma (37 papers, 2017 to 2026). A usually aggressive malignant neoplasm of the soft tissue or bone. "Capicua (CIC) is a gene that is frequently mutated in several cancer types, including stomach cancers and certain subtypes of brain tumours and sarcomas." (PMID 37345142, 2023). "CIC aberrations have recently begun to be associated with additional cancer types, such as sarcomas 19, 47, prostate cancer 36, and lung cancer." (PMID 28295365, 2017). "CIC-rearranged sarcomas are rare, high-grade, undifferentiated, small round cell sarcomas of bone and soft tissue classified by gene fusions involving the CIC gene with other gene partners, most commonly the DUX4 gene." (PMID 40599504, 2025). "Capicua transcriptional repressor (CIC)-rearranged sarcomas are undifferentiated, small, round cell sarcomas that are clinically aggressive and demonstrate poor response to chemotherapy." (PMID 40599504, 2025). "CIC::DUX4 sarcoma (CDS) is a lethal cancer driven by a fusion between tumor suppressor Capicua (CIC) and pioneer transcription factor double homeobox 4 (DUX4)." (PMID 41279843, 2025). "Round cell sarcomas with BCOR alterations usually harbor BCOR::CCNB3 and BCOR::MAML3 genetic fusions, and CIC-rearranged sarcomas are characterized by CIC::DUX4 chimeric transcript." (PMID 39021466, 2024). "Although the CIC::DUX4 fusion was the first CIC-rearranged sarcoma identified in 2006, there are still inadequate chemotherapy regimens utilized for CDS." (PMID 38882060, 2024). "Capicua transcriptional repressor (CIC)-rearranged sarcoma, belonging to the undifferentiated round cells sarcoma family, is characterized by high metastatic rate and poor chemo response." (PMID 36358827, 2022). "CIC sarcoma represents a new entity harboring the recurrent chromosomal translocation between CIC and, in most of the cases, DUX4." (PMID 36358827, 2022). "In recent years, a disease concept called ‘capicua transcriptional repressor (CIC) -rearranged sarcoma’ with gene rearrangement has been recognized." (PMID 32293288, 2020). "Capicua transcriptional repressor (CIC) -rearranged sarcoma is characterized by small round cells, histologically similar to Ewing sarcoma." (PMID 32293288, 2020). "CIC-rearranged sarcomas are molecularly defined, aggressive tumors." (PMID 40948502, 2025). "Diagnoses included RMS (n = 8; five alveolar and three embryonal), EWS (n = 5), clear cell sarcoma (n = 1), CIC Fusion with Double-Homeobox (DUX) Transcription Factors (CIC-DUX) fusion-transcript-positive sarcoma (n = 1), undifferentiated sarcoma (n = 1), and DSRCT (n = 1)." (PMID 32850366, 2020). "Some small round cell sarcomas previously considered atypical subtypes of Ewing sarcoma are genetically and clinically distinct entities and include CIC (Capicua Transcriptional Repressor)-rearranged sarcoma and sarcoma with BCOR (BCL6 corepressor) genetic alterations." (PMID 32225029, 2020). "These groups have been categorized as the round cell sarcomas associated with fusion forming EWSR1 (non-ETS fusions), the CIC (Capicua Transcriptional Repressor) rearrangement associated sarcomas, and BCOR (BCL-6 transcriptional co-repressor) associated sarcomas." (PMID 38954213, 2025). "The Capicua transcriptional repressor (CIC) rearranged sarcoma is a high-grade, undifferentiated sarcoma that occurs in the neural axis, characterized by recurrent translocations involving the CIC." (PMID 40255429, 2025). "Among these, protein capicua homolog (CIC)- and B-cell lymphoma 6 corepressor (BCOR)-rearranged sarcomas along with sarcomas carrying Ewing sarcoma breakpoint region 1 (EWSR1)-non-erythroblast transformation specific (ETS) fusions feature most prominently." (PMID 36158667, 2022). "In this review, we focus on the Capicua transcriptional repressor (CIC)-double homeobox 4 gene (DUX4) sarcoma (CDS), a high-grade sarcoma with poor outcome." (PMID 36358827, 2022).
sarcoma (continued). "The course of USRCS varies; CIC-rearranged sarcomas exhibit highly aggressive behavior, while the outcome of BCOR-CCNB3 sarcoma is similar to ES." (PMID 34698236, 2021). "These discordant cases included one single BCOR‐rearranged sarcoma (with a BCOR (exon 15)‐CCNB3 (exon 5) fusion gene detected by Archer) and one single CIC‐rearranged sarcoma (with CIC rearrangement detected by FISH)." (PMID 31965673, 2020). "According to the 2020 WHO Classification, undifferentiated small round-cell sarcomas include: Ewing sarcoma, round-cell sarcomas with EWSR1-non-ETS fusions, CIC-rearranged sarcomas, and BCOR-rearranged sarcomas." (PMID 34068344, 2021). "Among these, undifferentiated small round cell sarcomas (USRCSs) comprise multiple subcategories, including the recently described CIC-rearranged sarcomas, sarcomas with BCOR alterations, and non-ETS fused sarcomas (such as NFATC2 and PATZ1 sarcomas)." (PMID 38436779, 2024). "Currently, three categories are acknowledged: round cell sarcomas with EWSR1 gene fusion with non-ETS family members, CIC-rearranged sarcomas, and BCOR-rearranged sarcomas." (PMID 37720343, 2023). "This group of tumors can be subdivided into capicua transcriptional repressor (CIC)-rearranged sarcomas, Bcl6 corepressor (BCOR)-rearranged sarcomas, sarcomas with EWSR1 fusion to non-ETS family members, and unclassified round-cell sarcomas." (PMID 34068344, 2021). "In the latest WHO classification, undifferentiated small round cell sarcomas of bone and soft tissue are divided into four distinct categories: Ewing sarcoma (ES), round cell sarcomas with EWSR1::non-ETS fusions, sarcomas with BCOR genetic alterations, and CIC-rearranged sarcomas." (PMID 40722508, 2025).
astrocytomas (18 papers, 2012 to 2025).
Ewing sarcoma (11 papers, 2014 to 2025). A small round cell tumor that lacks morphologic, immunohistochemical, and electron microscopic evidence of neuroectodermal differentiation. "Capicua transcriptional repressor (CIC) is a transcription factor and in pediatric brain tumors a fusion was initially reported between CIC and NUTM1 in CNS Ewing sarcoma family of tumors with CIC alterations (CNS EFT–CIC)." (PMID 35169893, 2022). "Additional cytogenetic and molecular studies confirmed the presence of the CBFA2T3::GLIS2 fusion, but no Ewing sarcoma-specific EWSR1, FUS and CIC fusion transcripts were found." (PMID 40565358, 2025).
glioblastoma (9 papers, 2019 to 2024). The most malignant astrocytic tumor (WHO grade IV). "We found that CIC mutation has excellent diagnostic value in LGG, and that CIC mutation is mutually exclusive with glioblastoma, so we excluded the TCGA GBM cohort from further study." (PMID 32676453, 2020).
Intellectual disability (5 papers, 2018 to 2025). "Moreover, heterozygous loss-of-function mutations in CIC cause a rare neurodevelopmental syndrome characterized by prominent intellectual disability/learning difficulties in affected individuals." (PMID 34083623, 2021).
lung carcinoma (5 papers, 2017 to 2025). "Of note, CIC deletions as well as inactivating mutations were associated with metastasis of lung cancer cells." (PMID 41219537, 2025). "The CIC levels were slightly higher in lung cancer patients (5.16 (±7.46) ng/mL) than those of a healthy population (4.47 (±5.22) ng/mL)." (PMID 33143045, 2020).
angiosarcoma (4 papers, 2020 to 2024). A malignant tumor arising from the endothelial cells of the blood vessels. "The pathogenesis of angiosarcoma is probably also related to other genes, including CIC gene rearrangement, increased expression of the MYC gene and FLT-4 gene, and mutations of PTPRB and PLCG1, but the present study focused on the PD-1/PD-L1 and PI3K/mTOR signaling pathways." (PMID 34397726, 2021). "This heterogeneity in clinical behaviour might be related to the high genetic variability described in angiosarcomas, with several genes abnormalities identified in B-AS patients such as CIC, PLCG1, KDR and MYC." (PMID 32616718, 2020).
low grade glioma (3 papers, 2022 to 2023). A grade I or grade II glioma arising from the central nervous system.
colorectal cancer (2 papers, 2015 to 2023). A primary or metastatic malignant neoplasm that affects the colon or rectum. "For instance CIC mutation was reported in 6 out of 7 brain tumors, 3 out of 11 breast cancers and 6 out of 72 colorectal cancers." (PMID 26683696, 2015).
neuroepithelial tumors (2 papers, 2024 to 2025). "The 4 emerging neuroepithelial tumors were diagnosed based on detection of the CIC, PATZ1, and PLAGL1 fusion genes." (PMID 40980447, 2025). "Notably, within our cohort, we discovered two cases of neuroepithelial tumors with CIC::LEUTX fusion that demonstrated prolonged progression-free survival (PFS) and presented with unique, unassigned methylation signatures." (PMID 38926750, 2024).
oligodendroglial tumor (2 papers, 2014 to 2025). Oligodendrogliomas are cerebral tumors that are differentiated from other gliomas on the basis of their unique genetic characteristics and better response to chemotherapy. "A study researching CIC inactivating mutations sequenced DNA from 127 oligodendroglial tumors and found CIC mutations in 47% of the patients, with 59 out of 60 also having IDH mutations." (PMID 40564017, 2025).
prostate carcinoma (2 papers, 2015 to 2017). A carcinoma that arises from epithelial cells of the prostate gland. "We also tested whether deficiency of CIC could promote prostate cancer progression." (PMID 26124181, 2015). "CIC overexpression suppressed prostate cancer cell proliferation, invasion, and migration, whereas CIC RNAi exerted opposite effects." (PMID 26124181, 2015). "Overexpression of miR-93, miR-106b, and miR-375 increased cell proliferation and invasion, accompanied with down-regulation of CIC levels, suggesting the cancer promoting property of these three miRNAs in prostate cancer cells." (PMID 26124181, 2015). "CIC expression was markedly decreased in human prostatic carcinoma." (PMID 26124181, 2015). "Of the five miRNAs, we initially chose to evaluate miR-93, miR-106b, and miR-375, considering the number of putative binding sites for each miRNA in the 3′UTR of CIC and their frequency of overexpression in prostate cancer patients, and tested whether these miRNAs can down-regulate CIC levels." (PMID 26124181, 2015).